TGFB3 (transforming growth factor beta 3)
Diseases named in the same sentence as TGFB3 in open-access papers (continued):
Sharing a sentence is not in itself a finding about the gene and the disease.
preeclampsia (4 papers, 2020 to 2025). Preeclampsia is a hypertensive disorder of pregnancy that is characterized by new-onset hypertension with proteinuria presenting after 20 weeks of gestation, and depending on mild or severe forms may initially present with severe headache, visual disturbances, and hyperreflexia. "In contrast, it is reported that high TGFβ3 levels, but not TGFβ1 or TGFβ2 levels, can suppress trophoblast outgrowth, leading to shallow placental invasion and an increased risk of preeclampsia." (PMID 39791746, 2025). "Cardiac gene expression of Vcam, Edn1, Ccr2, Ctgf, Tgfb1, Tgfb2, Tgfb3, Bnp, Cybb, Mmp2, Mmp9, Timp1, Camk2a, Slc9a1, Nr3c2, and Nr3c1 was not different between mice who had a normal pregnancy and mice who had a preeclampsia-like pregnancy at 5 or 10 weeks postpartum (respectively)." (PMID 40425613, 2025). "However, the promoter binds the E2F4 transcription repressor, which is upregulated in preeclampsia via the activated HIF1A/TGFB3 axis." (PMID 41167398, 2025).
arrhythmogenic right ventricular cardiomyopathy (3 papers, 2012 to 2020). "Regulatory variants in TGFB3 have been associated with arrhythmogenic right ventricular cardiomyopathy." (PMID 26918958, 2016). "In humans, the TGFB3 gene is involved in arrhythmogenic right ventricular dysplasia (ARVD) familial 1 (ARVD1) (OMIM#107970), now being referred to as arrhythmogenic right ventricular cardiomyopathy (ARVC)." (PMID 32456345, 2020).
Autoimmunity (3 papers, 2015 to 2022). The occurrence of an immune reaction against the organism's own cells or tissues. "The isoform of TGFβ could also impact Th17 cells as TGFβ3 is more efficient than TGFβ1 in the induction of pathogenic Th17 cells leading to autoimmunity." (PMID 36016413, 2022). "These include Tgfb3, which is important in Th17-mediated autoimmunity, Igf1r, which is highly expressed in T-ALL cells, Rsad2 (viperin), which is a regulator of viral infection, Cd24a, which is important in T-cell homeostasis and Dusp16, which is a negative regulator of JNK in T-cells." (PMID 25908851, 2015).
cardiac hypertrophy (3 papers, 2022 to 2025). "In a murine model of cardiac hypertrophy, a pathology that involves fibrosis, Sox9, Tgfb2, and Tgfb3 were mutually upregulated and predicted to interact; however, this was not experimentally confirmed or linked to ECM regulation." (PMID 37510994, 2023). "The expression of Eln and Tgfb3 was used to calculate their correlation with the severity of cardiac hypertrophy." (PMID 35964009, 2022). "The level of Eln and Tgfb3 were significantly increased during the progression of cardiac remodeling and have a positive correlation with the severity of myocardial hypertrophy." (PMID 35964009, 2022). "Western blot analysis of the cardiac tissue of the cardiac hypertrophy mouse model revealed significantly increased Eln and Tgfb3 protein expression levels." (PMID 35964009, 2022). "In summary, we discovered a series of abnormally expressed genes in the development of cardiac hypertrophy and screened out the key genes, including Eln and Tgfb3." (PMID 35964009, 2022). "Additionally, suppression of cardiac hypertrophy was demonstrated by decreased expression of the hypertrophic marker ANP and the fibrosis-associated gene TGFβ3." (PMID 41322654, 2025). "Therefore, a more in-depth analysis is needed in the future to clarify the role of Tgfb3 in the process of myocardial hypertrophy." (PMID 35964009, 2022). "Upregulated key genes Eln and Tgfb3 were positively correlated with the severity of cardiac hypertrophy, which may provide potential therapeutic targets for the disease." (PMID 35964009, 2022). "However, in a rat model of aortic constriction (AC) induced cardiac hypertrophy, immunoblotting revealed that Tgfb3 levels decreased continuously in left ventricular tissue of hypertrophy rats starting from the 3rd-day post-operation, which seems to contradict our research." (PMID 35964009, 2022).
head and neck squamous cell carcinoma (3 papers, 2023 to 2025). A squamous cell carcinoma that arises from any of the following anatomic sites: lip and oral cavity, nasal cavity, paranasal sinuses, pharynx, larynx, and salivary glands. "For example, in the clinical management of head and neck squamous cell carcinoma (HNSCC), the levels of transforming growth factor-beta 3 (TGF-β3) protein were monitored as a biomarker for patient response to chemoradiation therapy (CRT)." (PMID 40006624, 2025).
malaria (3 papers, 2022 to 2025). Malaria is a serious and sometimes fatal disease caused by a parasite that commonly infects a certain type of mosquito which feeds on humans. "Furthermore, the same network identified KEGG terms related with protozoan infection, such as malaria, Chagas disease and leishmaniosis, pointing to a convergent set of genes (TGFB1, TGFB3, and TGFBR2) related with those infections and BV." (PMID 36985125, 2023).
Miscarriage (3 papers, 2021 to 2022). A pregnancy that ends at a stage in which the fetus is incapable of surviving on its own, defined as the spontaneous loss of a fetus before the 22th week of pregnancy. "AUB women with miscarriage history showed upregulation in MMP2, TGFB3 (P < 0.05), and downregulation in MMP9 and VEGFB (P < 0.05) expression compared to AUB group with no miscarriage history." (PMID 36564776, 2022). "Relative expression of MMP2 (0.15 ± 0.01) and TGFB3 (0.79 ± 0.02) increased significantly (P < 0.01) in AUB females with miscarriage history compared to AUB females with no miscarriage (0.07 ± 0.01, 0.11 ± 0.01) history respectively." (PMID 36564776, 2022). "In CG2, whose female partner suffered a miscarriage at 8 weeks, RNA analysis of spermatozoa identified 3 imbalanced genes involved in important DNA-binding transcription factor activity (RMI1) and embryogenesis (CBX2 and TGFB3)." (PMID 33877510, 2021).
rotator cuff tears (3 papers, 2020 to 2026). "Regarding the healing of rotator cuff tears it has already been shown that the sustained delivery of TGFB3 accelerated the healing process and in mouse Achilles’ tendons canonical TGFβ signaling has a functional role in tendon regeneration." (PMID 35203717, 2022).
scoliosis (3 papers, 2014 to 2021). A congenital or acquired spinal deformity characterized by lateral curvature of the spine. "This TGFB3 mutation (c.754+2T>C) segregated with the clinical phenotype and was also present in 1 young individual (1-IV:1, 17 years old) without documented cardiovascular features, but with mild systemic manifestations including craniofacial features, easy bruising, and scoliosis." (PMID 25835445, 2015).
tendinopathy (3 papers, 2021 to 2023). "In the DSLD case group, candidate genes included the candidate tendinopathy gene TGFB3 that was not shared with the DSLD phenotype-negative control group." (PMID 37645058, 2023).
triple-negative breast carcinoma (3 papers, 2019 to 2024). An invasive breast carcinoma which is negative for expression of estrogen receptor (ER), progesterone receptor (PR), and human epidermal growth factor receptor 2 (HER2). "In vivo, genome-wide CRISPR LOF screen has identified TGFβ3 as an actionable biomarker of palbociclib resistance in triple negative breast cancer." (PMID 39696697, 2024).
urothelial carcinoma (3 papers, 2019 to 2024). A malignant neoplasm derived from the transitional epithelium of the urinary tract (urinary bladder, ureter, urethra, or renal pelvis). "TGFB3, also known as transforming growth factor-B3, was associated with anti-PD-L1 monoclonal antibody treatment in urothelial carcinoma." (PMID 38336764, 2024). "Furthermore, a low expression level of TGFB3 was associated with complete or partial response to anti-PD-L1 monoclonal antibody treatment in urothelial carcinoma, resulting in a good prognosis." (PMID 36003383, 2022). "The inhibition of TGFB3 in urothelial carcinoma may be a potential target to overcome immunotherapy resistance." (PMID 36003383, 2022). "Finally, the immune landscape of urothelial carcinoma showed the immune status in each patient, and TGFB3 was identified as a potential biomarker for the prediction of immunotherapy resistance after anti-PD-L1 monoclonal antibody treatment." (PMID 36003383, 2022).
arachnodactyly (2 papers, 2023 to 2024). "Genetic variants in genes including TGFBR1, TGFBR2, TGFB2, TGFB3, SMAD2, and SMAD3 result in Loeys–Dietz syndrome and are reported to cause Marfan-like phenotypes and variants in FBN2 and COL3A1 result in congenital contractural arachnodactyly and Ehlers–Danlos syndrome type IV." (PMID 38791509, 2024).
bladder cancer (2 papers, 2015 to 2025). "Here, we unveiled new therapeutic targets of TGN, TGFβ3-associated signaling in cisplatin-resistant bladder cancer cells." (PMID 40027190, 2025). "Our preliminary research from the TCGA bladder cancer database revealed that patients with high expression of TGFβ3 were significantly associated with a lower overall survival rate than patients with a lower TGFβ3 expression." (PMID 40027190, 2025). "From a pan-cancer large-scale analysis 15, we could further extrapolate that GLI2 is most significantly associated with TGFβ3 in bladder cancer patients, laying the foundation for this study." (PMID 40027190, 2025). "A recent study suggested that TGFβ3 was co-expressed with other hub genes to form an oncogenic network in bladder cancer." (PMID 40027190, 2025). "This is supported by our gene silencing data, where TGFβ3-silenced bladder cancer cells exhibited a markedly reduced ability to generate CAFs and tumorspheroids (stemness and drug resistance)." (PMID 40027190, 2025). "We started with a bioinformatics approach and identified a novel gene signature, TGFβ3/GLI2/YAP1 (the TGY) signature, significantly associated with immune evasion and therapy resistance in bladder cancer." (PMID 40027190, 2025). "TGFβ3-silenced bladder cancer cells demonstrated a significantly reduced self-renewal ability as reflected by the significantly low number of tumorspheroids generated compared to their control counterparts." (PMID 40027190, 2025). "Collectively, the bioinformatics analysis identified TGFβ3/GLI2/YAP1 as a potential target gene signature (TGY signature) in bladder cancer." (PMID 40027190, 2025). "In summary, our study identifies a unique TGFβ3/GLI2/YAP1 (the TGY signature) that is not only elevated in bladder cancer cells but also plays a crucial role in CAF transformation and function." (PMID 40027190, 2025). "According to our bioinformatics results, TGFβ3 is also significantly expressed higher in the bladder cancer cells." (PMID 40027190, 2025). "Notably, the GLI2 demonstrated a higher correlation (cor = 0.61, p<0.001) with TGFβ3 in bladder cancer when compared to other cancer type." (PMID 40027190, 2025). "The silencing of TGFβ3 resulted in reduced CAFs, further supporting TGFβ3's role in CAF transformation in the context of bladder cancer." (PMID 40027190, 2025).
dyslipidemia (2 papers, 2018 to 2021). "Likewise, Tgfb3+/− mice showed neither dyslipidemia nor hypercholesterolemia compared with Tgfb3+/+ mice." (PMID 34431499, 2021).
endometrial tumors (2 papers, 2009 to 2010). "Moreover, Tgfb3 was also found among the top 10 genes with differential expression between endometrial tumors and non-/pre-malignant endometrium." (PMID 19426485, 2009).
gastric cancer (2 papers, 2019 to 2022). A primary or metastatic malignant neoplasm involving the stomach. "In view of the important role of TGFβ in EMT, we used small interfering RNA (siRNA) to reduce TGFβ1, TGFβ2 and TGFβ3 gene expression in gastric cancer cells." (PMID 36119489, 2022). "Firstly, immunohistochemical experiments were performed on paraffin sections of gastric cancer to observe the main distribution of TGFβ1, TGFβ2 and TGFβ3 proteins in gastric cancer tissues." (PMID 36119489, 2022). "To verify the promoting effect of TGFβ on EMT, we added TGFβ1, TGFβ2 and TGFβ3 active proteins to the culture medium, respectively, and cultured gastric cancer cells in TGFβ environment to detect the changes of cancer cell phenotype." (PMID 36119489, 2022). "Transwell assay examined the change of gastric cancer cell migration ability in TGFβ experimental group and control group (HSA), and the migration ability of gastric cancer cells was enhanced under TGFβ1, TGFβ2 and TGFβ3 active protein stimulation conditions." (PMID 36119489, 2022). "In contrast, the migration ability of gastric cancer cells was reduced and statistically significant after silencing of TGFβ1, TGFβ2 and TGFβ3 genes." (PMID 36119489, 2022). "The results showed that in gastric cancer TGFβ1, TGFβ2 and TGFβ3 expressions were strongly correlated with most of the immune cell infiltration levels." (PMID 36119489, 2022). "TGFβ1, TGFβ2 and TGFβ3 were significantly positively correlated with immune cell infiltration in multiple gastric cancer datasets." (PMID 36119489, 2022). "In this study, we analyzed the transcriptomic dataset GSE184336 of 231 gastric cancer patients, and the results showed that TGFβ1, TGFβ2 and TGFβ3 were highly expressed in cancer tissues, and western blot assays further confirmed the differences in TGFβ expression." (PMID 36119489, 2022). "In this study, we comprehensively analyzed TGFβ1, TGFβ2 and TGFβ3 and gastric cancer microenvironmental features, including immune cell infiltration, EMT, hypoxia, mutation, immunotherapy and drug treatment, based on HMUCH sequencing data (GSE184336) and public databases." (PMID 36119489, 2022). "However, the potential functions and mechanisms of TGFβ1, TGFβ2 and TGFβ3 in gastric cancer progression and tumor immunology are unclear." (PMID 36119489, 2022). "In gastric cancer dataset STAD, GSE63089 and dataset GSE184336, the expression levels of TGFβ1, TGFβ2 and TGFβ3 were higher in cancer tissues than in normal tissues adjacent to the cancer." (PMID 36119489, 2022). "The results of this study showed that TGFβ1, TGFβ2 and TGFβ3 were positively correlated with EMT, CDH2, VIM and ZEB1 and significantly negatively correlated with CDH1 in multiple gastric cancer datasets." (PMID 36119489, 2022). "Thus, after silencing the TGFβ gene in gastric cancer cells, the progression of EMT was significantly inhibited, and all of these results together suggest that TGFβ1, TGFβ2 and TGFβ3 are key factors in regulating the progression of EMT." (PMID 36119489, 2022).
Glucose intolerance (2 papers, 2020 to 2022). Glucose intolerance (GI) can be defined as dysglycemia that comprises both prediabetes and diabetes. "Moreover, mice with tgfβ3 haploinsufficiency that are fed an HFD show increased glucose intolerance and weight gain in vivo compared to their wild-type littermates." (PMID 36425072, 2022).
hepatocellular carcinoma (2 papers, 2019 to 2021). A malignant tumor that arises from hepatocytes. "Moreover, the term “Hepatocellular carcinoma” is enriched with FZD8, ribosomal protein S6 kinase alpha-6 (PRSAKA6), TGFB3 and GSTM1." (PMID 34150612, 2021).
Insulin resistance (2 papers, 2021 to 2022). Increased resistance towards insulin, that is, diminished effectiveness of insulin in reducing blood glucose levels. "The lipotoxicity caused by the accumulation of lipids in the kidney likely caused insulin resistance in Tgfb3+/− mice, as suggested by the absence of AKT phosphorylation in kidney extracts." (PMID 34431499, 2021).
liver cancer (2 papers, 2021 to 2025). An epithelial or non-epithelial malignant neoplasm that arises from the liver. "Mediation MR indicated that cheese intake influenced liver cancer risk indirectly by modulating TGFB3, EPOR, ELANE, and C3 expression, accounting for 8.8%, 25%, 1.8%, and 12.7% of the total effect, respectively." (PMID 40895144, 2025). "MR findings suggest that higher cheese intake is associated with reduced liver cancer risk, with partial mediation through modulation of TGFB3, EPOR, ELANE, and C3 expression." (PMID 40895144, 2025). "This study uncovers a potential molecular mechanism by which FODMAP‐related dietary patterns may modulate liver cancer risk through the TGFB3/EPOR/ELANE/C3 signaling axis." (PMID 40895144, 2025). "The inverse association between cheese consumption and liver cancer risk may be partly explained by TGFB3's capacity to modulate inflammatory pathways, potentially suppressing tumorigenesis." (PMID 40895144, 2025). "Protein‐level analyses identified four trogocytosis‐ and efferocytosis‐related proteins, TGFB3, EPOR, ELANE, and C3, that may mediate these dietary effects on liver cancer susceptibility." (PMID 40895144, 2025). "Using a two‐step MR framework, we evaluated whether TGFB3, EPOR, ELANE, and C3 mediate the causal association between FODMAP dietary intake and liver cancer risk." (PMID 40895144, 2025). "Moreover, we found that PMEPA1 mRNA expression is upregulated in human HCC samples, and its level correlates with TGFβ1, TGFβ2, and TGFβ3 mRNA expression in TCGA liver cancer samples." (PMID 33608500, 2021). "The MR results revealed significant associations between three FODMAP dietary components, cheese, cereal, and dried fruit intake, and six liver cancer‐related proteins (ANXA2, SFTPD, TGFB3, EPOR, ELANE, and C3)." (PMID 40895144, 2025). "Furthermore, these findings emphasize the pivotal roles of TGFB3, EPOR, and ELANE in liver cancer, especially regarding dietary factors such as cheese intake." (PMID 40895144, 2025).
male infertility (2 papers, 2015 to 2021). The inability of the male to effect fertilization of an ovum after a specified period of unprotected intercourse. "The association of TGFB3 polymorphism with male infertility can be also explained by other findings of the present study." (PMID 26612435, 2015). "In conclusion, the results of the present study may suggest an association between TGFB3 polymorphism and male infertility." (PMID 26612435, 2015). "The results indicate that variants in TGFB3 gene may be associated with male infertility." (PMID 26612435, 2015). "The aim of this study was to investigate the potential association between TGF-β3 (TGFB3) and TNF-α (TNF) gene polymorphisms and male infertility." (PMID 26612435, 2015). "Therefore, the present study evaluated associations between polymorphisms of genes coding for TNF-α and TGF-β3, i.e. TNF and TGFB3, and male infertility." (PMID 26612435, 2015).
mitral valve disease (2 papers, 2015 to 2020). "We demonstrate that TGFB3 mutations are associated with significant cardiovascular involvement, including thoracic/abdominal aortic aneurysm and dissection, and mitral valve disease." (PMID 25835445, 2015).
myoma (2 papers, 2021 to 2024). "In fact, a direct link was reported between myoma-derived transforming growth factor beta-3 and HOXA10 downregulation." (PMID 39274229, 2024). "In contrast, other researchers observed higher levels of TGFβ3 in myoma tissue and emphasized the importance of this growth factor in the proliferation of ECM." (PMID 34442017, 2021).
oral squamous cell carcinoma (2 papers, 2019 to 2023). "Previous laser capture microdissection studies in both CRC and oral squamous cell carcinomas show that tumor buds over-express EMT-related genes such as ZEB1, ZEB2, DES, TGFB3, and VIM in comparison to the main tumor mass." (PMID 31316988, 2019).
Peri-Implantitis (2 papers, 2025). An inflammatory process with loss of supporting bone in the tissues surrounding functioning DENTAL IMPLANTS. "The qualitative evidence indicates that certain polymorphisms—particularly in the CD14, TNFα, IL-1, and EGF genes—show consistent associations with increased susceptibility to peri-implantitis, while others (e.g., MMP13, TGFB3, RANKL) demonstrate no clear relationships." (PMID 41373620, 2025).